IGF1 (insulin like growth factor 1)
Diseases named in the same sentence as IGF1 in open-access papers (continued):
Sharing a sentence is not in itself a finding about the gene and the disease.
cancer (continued). "In addition to its direct involvement in cancer cell survival and proliferation, the IGF1/IGF1R axis is also appearing as a key factor involved in the regulation of immunity and may be an important player in modulating the immune-compartment of the TME, and thus, the cancer-related immune response." (PMID 38420122, 2024). "While IGF1 reduction was attributed to non-specific surgical effects, the IGF2 decrease remained significant, especially for malignant tumours and larger sizes." (PMID 38339282, 2024). "Additionally, IGFBP-2 is upregulated in several cancers and promotes several pathways involved in oncogenic signaling, including the stimulation of proliferation, epithelial–mesenchymal transition, invasion, metastasis, and angiogenesis, all of which are independent of IGF-1." (PMID 38137390, 2023). "Thus, scLCDV1-VILP is a natural peptide with specific antagonist properties on IGF1R signaling and may provide a new tool to guide development of hormonal analogues to treat cancers or metabolic disorders sensitive to IGF-1 without affecting glucose metabolism." (PMID 36335114, 2022). "The expressions of IGF-1/IGF-1R share negative correlation with TMB and MSI in most cancer types, which means high expression of IGF-1/IGF-1R indicates immunosuppression." (PMID 34804946, 2021). "As an alternative strategy to target IGF signaling, results of phase 1 clinical trials of the dual IGF1/2-neutralizing antibodies have been reported, while no results of phase 2/3 trials in cancer therapy have been reported." (PMID 32493414, 2020). "IGFBP-1 is one of six IGF binding proteins that bind to and stabilize IGF proteins in circulation; they can have both positive and negative effects on IGF function, but IGFBP-1, specifically, has been reported to inhibit IGF-1 promotion of cancer progression." (PMID 32469992, 2020). "The RNA levels of Abcb1a, Abcg1 and Abcg2, some of the most studied drug transporters in cancer, were elevated in bGH and GHRKO mice, both of which have elevated circulating GH irrespective of the levels of IGF-1." (PMID 33291663, 2020). "Serum glucose, HbA1c, IGF-1, IGFBP3 and HOMA were not independently related to long-term cancer mortality." (PMID 23405181, 2013). "IGF-1 and TGF-β1 were required for growth stimulation by CAF from low-grade but not high-grade carcinomas, indicating a grade-dependency of paracrine signaling pathways." (PMID 23056402, 2012). "In the mouse skin model, IGF-1 mRNA levels are elevated consistently in papillomas and carcinomas, while IGF-1R mRNA is up-regulated in some but not all tumors, mostly carcinomas." (PMID 21297902, 2010). "Our results show that none of the growth factors measured (IGF1, IGF2 or IGFBP3) have any value in cancer screening in men." (PMID 16804529, 2006). "We therefore are confident that the general conclusion that none of the growth factors measured (IGF1, IGF2 or IGFBP3) have any value in cancer screening can be extended to all the main cancers in men and women." (PMID 16804529, 2006). "The implementation of a KD intervention in cancer patients did not result in significant changes in the following nine indicators: HDL cholesterol, triglycerides, CRP, IGF-1, TNF-α, creatinine, urea, energy intake, and age at the time of the dietary intervention." (PMID 40756563, 2025). "In conclusion, the exercise contributes to the reprogramming of intermediate metabolism in cancer cells/tissue through the activation of AMPK, IGF-1 and IGF-1R resulting in a potential nonpharmacological adjuvant in the management and treatment of some types of cancer including LC." (PMID 39555455, 2024). "Indeed, we found that 50% and 64% of co-cultures with CAF from low-grade (grade 1 or 2) carcinomas responded to antibodies blocking IGF-1 and TGF-β1, respectively, whereas all co-cultures with CAF from high-grade (grade 3) carcinomas failed to respond to these inhibitors." (PMID 23056402, 2012).
tumor (2,183 papers, 1992 to 2026). "The insulin-like growth factor-1 (IGF-1) axis has been implicated in tumour proliferation, survival, and treatment resistance." (PMID 41636865, 2026). "This review elucidates the significance of IGF1 isoform expression in physiology and pathogenesis, in addition to the mechanisms by which IGF1 spliced variants contribute to tumour biology and their potential as a target in EC research." (PMID 39796756, 2025). "Preclinical studies have shown that periodic cycles of the FMD significantly lower IGF-1 levels, making tumor cells more susceptible to stress and less capable of resisting apoptosis." (PMID 39940361, 2025). "Resistance to CSF-1R inhibitors is likely mediated through the interaction of insulin-like growth factor-1 (IGF-1) and tumor cell IGF-1 receptor (IGF-1R), causing an upregulation of the phosphoinositide 3-kinase (PI3K) pathway." (PMID 40427130, 2025). "Lower levels of IGF-1, in particular, have been associated with reduced tumor growth and improved responses to chemotherapy." (PMID 40296920, 2025). "Conversely, GH and IGF-1 deficits are associated with a diminished incidence of tumor promotion, associated to IGF-1/IGF-1R." (PMID 41221256, 2025). "Metabolic syndromes, hormonal imbalances, and sex steroid milieu have been linked to IGF1 signalling activation in endocrine-related tumour progression." (PMID 39796756, 2025). "Supraphysiological circulating IGF-1 levels increase the risk of several diseases, including some tumours (e.g., colon carcinoma), and they also accelerate ageing in serum, as demonstrated by the studies evaluating biological age." (PMID 40507601, 2025). "Typically, patients bearing GNAS mutations present with smaller tumor sizes, higher GH and insulin-like growth factor 1 (IGF-1) levels and better responses to neurosurgeries." (PMID 39513543, 2025). "Other biomarker classes, including TNF-receptor signaling, CRP and systemic inflammation indices (NLR, SII, and PIV), IGF-1, CD markers, tumor-associated antigens, and BDNF, were likewise inconsistently related to cognition." (PMID 41228315, 2025). "This review delves into the roles of IGF1 and its variants; IGF1-Ea, IGF1-Eb, and IGF1-Ec, and their interactions with hormones like oestrogen in driving tumour growth and spread." (PMID 39796756, 2025). "B cell secretion of IGF1 then causes tumor cells to activate FGFR3 signaling and adopt stem-like properties." (PMID 40663561, 2025). "These diets not only improve metabolic health but also modulate the tumor microenvironment by reducing inflammation and oxidative stress, which are closely linked to insulin and IGF-1 signaling." (PMID 40428567, 2025). "In this model, the loss of DACH1 is tumor cells enhances the secretion of IGF1, which in turn binds and activates the IGF1R and downstream signaling in TAMs." (PMID 38892104, 2024). "In children treated with human recombinant GH for short stature, risk of serious adverse reaction including tumor increases in patients with IGF-1 level above 2 standard deviation score." (PMID 39403490, 2024). "Conversely, recent evidence strongly indicates that the IGF-1/IGF-1R signaling pathway plays a significant role in promoting tumor metastasis and drug resistance associated with epithelial-to-mesenchymal transition (EMT)." (PMID 39638246, 2024). "In contrast to SSTR2, IGF-1R has been implicated in tumor growth, invasion, and metastasis, and the binding of IGF-1 and IGF-1R triggers a proliferative and anti-apoptotic signaling cascade." (PMID 39238765, 2024). "The insulin/IGF1 growth axis has been implicated as a poor prognostic marker, not as an oncogenic pathway, but as a proliferative additive to the unregulated tumor cell signal." (PMID 39195514, 2024). "The GHRA dose in the current study is thus physiologically relevant but lower than most previously used doses of pegvisomant in nude mouse tumor xenograft studies aimed at causing significant serum IGF1 reduction in mice." (PMID 39000545, 2024).
tumor (continued). "Recent studies have focused mainly on controlling hyperinsulinaemia and exploring the insulin-like growth factor-1 (IGF-1) related to tumor promotion caused by IR." (PMID 39737155, 2024). "Tumor-associated macrophages produce IGF-1 and hepatocyte growth factor (HGF), determining the proliferation of neoplastic cells and the recruitment of monocytes and the proliferation of neoplastic cells." (PMID 38791916, 2024). "The activation of the epidermal growth factor receptor (EGFR) signaling pathway promotes the secretion of insulin-like growth factor-1 (IGF-1), which in turn induces tumor-associated macrophage polarization." (PMID 39619695, 2024). "Although not considered an oncogene, elevated blood IGF-1 levels, and more importantly, local or peritumoral IGF-1 levels, have been associated with poor prognosis, increased tumor growth, and resistance to cytotoxic therapy." (PMID 39195514, 2024). "Elevated adiposity and altered IGF-1 levels are also linked with OC, where insulin’s tumor-enhancing effects often activate the PI3K/Akt-mTOR pathway, a key regulator of cell growth, proliferation, and survival." (PMID 39596005, 2024). "Due to the association between IGF-1 and tumor growth, the therapeutic use of this growth factor has been approached with great caution." (PMID 39638246, 2024). "Consistent with our previous findings, addition of IGF1 increased viability of T-ALL cells only in the presence of tumor-associated myeloid cells." (PMID 37805579, 2023). "GH and insulin-like growth factor-1 (IGF-1) have mitogenic and anti-apoptotic properties, which is associated with the suspicion that they can induce tumor formation." (PMID 37765128, 2023). "In SHH MBL, tumour-associated microglia occupy a different niche, instead driving tumour progression by secreting insulin-like growth factor 1 (IGF1)." (PMID 37232837, 2023). "IGF-1 causes upregulation of the PI3K (phosphoinositide 3-kinase) pathway in tumor cells by binding to IGF-1R." (PMID 37598273, 2023). "Younger age was associated with a low probability of achieving long-term IGF-1 normalization; in addition, the preoperative growth rate is associated with age, residual tumor volume with older age, gender and suprasellar CS extension." (PMID 37371013, 2023). "Supplying exogenous IGF1 enhances survival of T-ALL cells co-cultured with tumor-associated myeloid cells." (PMID 37805579, 2023). "Adiposity is also implicated in the production of tumor growth factors, such as insulin-like growth factor 1 (IGF-1), and in resistance to the cytotoxic effects of CHT due to a protective effect on tumoral cells." (PMID 36771416, 2023). "While Il4r and Igf1 mRNA was expressed in Cd68/Aif1-positive tumour-associated microglia throughout drug-treated PDOX, Il4 expression co-localised with Gfap/S100b-expressing astrocytes exclusive to the interface region of drug-treated PDOX." (PMID 37127652, 2023). "Preclinical results suggest that enhanced tumor immunity and decreased growth signaling, via lowering of circulating insulin and insulin growth factor 1 (IGF-1) levels form the potential underlying mechanisms." (PMID 35326541, 2022). "These trans-differentiated astrocytes secrete IL-4 and polarize tumor-associated microglia to produce IGF-1, which in turn stimulates tumor progression by accelerating migration and adhesion." (PMID 36291792, 2022). "The IGF1 gene was downregulated in tumor fibroblasts and the low expression was associated with poor prognosis." (PMID 36357663, 2022). "The association of insulin-like growth factor (IGF)-1 axis expression pattern with the patient’s clinical pathological characteristics and tumor aggressive features, the diagnostic and predictive values were assessed for all tumor groups." (PMID 36713521, 2022). "IGF-1 induces Ras-Raf-MAPK and PI3K-AKT signalling components to promote tumour progression and elevated levels of serum IGF-1 was associated with poor prognosis." (PMID 34997107, 2022).
tumor (continued). "In multivariable MR, BMR was consistently positively associated with neoplasm after adjusting for IGF1 overall, in men, and in women." (PMID 34567085, 2021). "Pegvisomant bases its efficacy on blocking the activity of the GH-R, thereby inhibiting the synthesis of IGF-1 and, therefore, potentially reducing the risk of tumor development." (PMID 33713207, 2021). "Using the two‐tiered system, a good response to SSA was significantly associated with older age, higher IGF1 levels at the time of presentation, a smaller tumour size and higher expression of E‐cadherin and SSTR2A." (PMID 33491286, 2021). "Individuals with GHR deficiency (GHRD) caused by genetic mutations in the displayed GHR gene and congenital IGF1 appear to be protected against the development of neoplasms." (PMID 34178997, 2021). "Numerous animal models have shown that caloric restrictions are associated with a decrease of IGF-1 serum levels, resulting in the anti-tumor and anti-aging activity of IGF-1 (reviewed in:)." (PMID 34208601, 2021). "On the contrary, higher IGF-1 xULN values at diagnosis (OR 2.304, p=0.007) and a T2-hypointense tumor (OR 18, p=0.017) were associated with a significantly higher likelihood of achieving >50% IGF-1 reduction after SRL therapy." (PMID 34025586, 2021). "Factors significantly associated with SSA treatment outcome included age, IGF1 levels, tumour size and expression of E‐cadherin and SSTR2A." (PMID 33491286, 2021). "An association between plasma insulin/IGF-1 concentrations and tumor development is widely acknowledged." (PMID 33802978, 2021). "IGF-1 serum concentrations are expected to be reduced by drug treatment and, therefore, potentially reducing the risk of tumor development." (PMID 33713207, 2021). "CR associates with marked reductions in serum IGF-1 levels with many other benefits of CR, such as decreased tumor incidence and metabolic abnormalities in rodents." (PMID 33919674, 2021). "The IGF‐1 gene rs2195239 polymorphism was associated with the tumor size, TNM stage, and adenocarcinoma among GC patients." (PMID 32147868, 2020). "Among the known IGF1 mRNA variants and IGF1 precursor proteins, a clearly mitogenic role in tumor biology is attributed to the IGF1Ec isoform." (PMID 32977489, 2020). "This review highlights the role of IGF1 isoform expression (mRNAs, proteins) in different types of human tumors, as well as the mechanisms of IGF1 spliced variant involvement in tumor biology." (PMID 32977489, 2020). "Divergent associations of IGF1 with all-cause mortality were observed between tumor size ≤2 cm and >2 cm, with a borderline significant interaction (P for interaction = 0.06)." (PMID 32974138, 2020). "IGF-1 promotes a series of intracellular signaling cascades leading to mitogenic and antiapoptotic events, a risk factor for recurrence and tumor growth." (PMID 31052303, 2019). "Dysregulation of GH–IGF-1 axis can amplify the synergistic effect of GH and IGF-1 to promote uncontrolled cell proliferation, cell movement, angiogenesis, and suppress apoptosis to increase risk of neoplasia." (PMID 29487568, 2018). "The PDAC hypoxic tumor microenvironment also induced the production of IGF1 by cancer-associated fibroblasts (CAFs) and the expression of IGF1R in PDAC cells." (PMID 30366466, 2018). "High levels of circulating IGF-1 have been linked to an increased risk of neoplasia and poor prognosis in many clinical studies." (PMID 29983893, 2018). "In all patients, increased cytoplasmic IGF-1 expression significantly associated with increased tumour size (P = 0.030)." (PMID 30337563, 2018). "In our studies on GHRH antagonists, we have previously shown an association between the levels of serum or tumoral IGF-1 and tumor growth." (PMID 29983893, 2018). "Significant associations were found for tumor size, preoperative T4, IGF-1, FSH, LH and urinary-free cortisol." (PMID 28916976, 2018).
tumor (continued). "Here, the authors describe a potential mechanism of acquired drug resistance mediated by tumor-associated B cells-derived IGF-1." (PMID 28928360, 2017). "It is possible that these specific mutations contribute (in)directly to the X10/IGF1 phenotypes and enhanced tumor development and progression." (PMID 28173837, 2017). "ARK5 has been also reported to act as a tumor invasion-associated factor through NDR2 during IGF-1 signaling." (PMID 26882569, 2016). "Increased IGF-1 levels are associated with an elevated BC mortality and with inherent resistance to anti-tumor treatments in preclinical models." (PMID 26738606, 2016). "SAGIT combines signs and symptoms, associated comorbidities, GH levels, IGF-1 levels, and tumour profile." (PMID 27716353, 2016). "SNPs of the IGF1R (rs12423791), and IGF1 (rs2162679, rs5742612, rs35767) genes were significantly associated with tumor response to FOLFOX." (PMID 27144430, 2016). "At least one SNP in IGF1R (rs12423791) and three SNPs in IGF1 (rs2162679, rs5742612, rs35767) were associated with tumor response to chemotherapy." (PMID 27144430, 2016). "Several SNPs of the IGF1R (rs12423791), and IGF1 (rs2162679, rs5742612, rs35767) genes were significantly associated with tumor response." (PMID 27144430, 2016). "Here, we have developed an immunohistochemical method to detect CCL5 and IGF-1 in tumor-associated adipose tissue specimens." (PMID 27027351, 2016). "An association between IGFBP and ERBB2 in IGF-1-dependent tumor transformation has been reported in mammary luminal epithelial cells." (PMID 25743390, 2015). "It has been demonstrated that in vitro E2 and IGF-1 co-regulate a number of genes comprised mainly of tumor suppressing factors associated with poor disease outcome." (PMID 25743390, 2015). "The association of IGF-1 with disease prognosis following tumor establishment is also currently under investigation." (PMID 25743390, 2015). "S6K2 and 4EBP1 were inversely associated with IGF1 levels, and their prognostic value was shown to be restricted to tumours positive for IGFR and/or HER2." (PMID 26698305, 2015). "On the other hand, the mice group on CRD exhibited the least tumor burden associated with a significant reduction in levels of insulin, IGF-1, leptin, MCP-1, VEGF and IL-6." (PMID 25026276, 2014). "On the other hand, high/normal levels of GH/IGF-1 during aging have been associated with the development of neoplastic disease in both human and animals, and complete lifelong suppression of GH signaling in rodents produces robust extension of longevity." (PMID 24341939, 2014). "The causal and important role of this pathway in promoting tumor progression is exemplified by the fact that CR combined with IGF-1 administration or constitutive PI3K activation through genetic mutations rescues tumors from growth inhibition induced by CR." (PMID 24436017, 2014). "Higher IGF-1 levels were associated with and increased risk of second primary tumours with a hazard ratio of 2.78 (95%CI: 1.62–4.77)." (PMID 25047238, 2014). "Univariate analysis indicated that the elevated mRNA levels of both SSTR2 and RORC were associated with a larger decrease in IGF-1 levels and tumor reduction." (PMID 23825587, 2013). "To better delineate the relationship between glucose status and underlying tumor pathology we next examined the impact of glucose metabolism and IGF-1 normalization to assess possible interactions." (PMID 24039977, 2013). "We have also shown that tumor development in liver-specific IGF-1 deficient (LID) mice, which have a ∼75% reduction in systemic IGF-1 levels relative to wild-type mice, is inhibited to levels observed in wild-type mice on a CR regimen." (PMID 23342276, 2012). "They reported that VEGF was correlated to tumor grade, nodal involvement, vascular invasion, metastases and stage; bFGF was associated with tumor size and grade; and IGF-1 was correlated with vascular invasion." (PMID 24212642, 2011).